PDCD4 (programmed cell death 4)
Diseases named in the same sentence as PDCD4 in open-access papers (continued):
Sharing a sentence is not in itself a finding about the gene and the disease.
colon carcinoma (continued). "PDCD4 is also a known target of miR-21 in several types of cancer (colon cancer or diffuse large B-cell lymphoma), including PDAC." (PMID 29464088, 2018). "It was previously reported that the loss of PDCD4 induced apoptosis in HeLa cells and C2C12 myoblasts but promoted cell proliferation in HT29 colon tumor cells." (PMID 30687637, 2018). "miR-21 can promote the intravasation of colon cancer cells by targeting tumor suppressor gene programmed cell death 4 (PDCD4)." (PMID 26064956, 2015). "PDCD4 inhibited colon cancer cell invasion through suppressing mitogen-activated protein kinase kinase kinase kinase 1 (MAP4K1), leading to suppressed AP-1 dependent transcription." (PMID 22272332, 2012). "In colon carcinoma, PDCD4 over-expression was shown to decrease the invasive potential of cancer cells, and its under-expression enhanced cancer cell invasion." (PMID 20831814, 2010). "Similar to our findings, PDCD4 suppressed the invasion and intravasation of colon cancer cells, implicating PDCD4 as regulator of invasion and metastasis." (PMID 20831814, 2010). "Other mechanistic studies in colon cancer showed that PDCD4 knock-down activates β-catenin/Tcf-dependent transcription and acts as a promoter of tumor cell invasion." (PMID 20831814, 2010). "A recent study showed that PDCD4 suppressed tumor progression in human colon carcinoma cells by the novel mechanism of down-regulating MAP4K1 transcription, with consequent inhibition of c-Jun activation and AP-1-dependent transcription." (PMID 18570662, 2008). "Loss of PDCD4 is associated with tumour progression and prognosis while overexpression of PDCD4 in human colon carcinoma cells is able to suppress tumour progression by inhibiting c-Jun and AP-1 pathways." (PMID 16919171, 2006). "Moreover, PDCD4 downregulation stimulates cell proliferation in colon carcinoma and glioblastoma-derived cells, thereby facilitating tumor growth." (PMID 41439995, 2025). "Inhibition of AR was found to prevent the growth of HT29, SW480, and Caco-2 colon cancer cells and nude mice xenografts by downregulating miR-21 expression with concomitant upregulation of programmed cell death 4 (PDCD4), a target of miR-21 by modulation of the ROS/AMPK/mTOR/AP1/4E-BP1 pathway." (PMID 39055885, 2024). "miR-21 enriched with exosomes derived from colon cancer cells could inhibit PDCD4 protein translation involved in cell apoptosis." (PMID 37373600, 2023). "Also, the inhibition of COX-2 in HCA-7 colonic carcinoma cells results in decreased miRNA-21 and increases PDCD4, whereas treatment with prostaglandin E2 (PGE2) has the opposite effect." (PMID 35847932, 2022). "In other cell types, decreased PDCD4 expression in HT29 colon carcinoma cells is associated with an increase in β catenin/T-cell factor (TCF)- and AP-1-dependent transcription, whereas increased exogenous PDCD4 in lung results in decreased AP-1 and increased apoptosis." (PMID 35847932, 2022). "As a novel tumor suppressor gene, programmed cell death 4 (PDCD4) could regulate multiple signal transduction pathways of colon cancer, thus inhibiting tumor progression at the transcriptional and translational levels." (PMID 33996533, 2021). "PDCD4 could overcome the resistance to an IGF-1R/IR Inhibitor in colon carcinoma cells, which could be used for the treatment of colon cancer." (PMID 32962686, 2020). "A mutation in the c-Myc binding site of the MAP4K1 promoter could reduce MAP4K1 promoter activity, and the downregulation of c-Myc can restore MAP4K1 expression and the activation of AP1 in PDCD4-knockdown colon tumor GEO and HT29 cells." (PMID 31620370, 2019). "Interestingly PDCD4, suppresses tumor progression in human colon carcinoma cells by down-regulating the MEK kinase kinase 1 (MAP4K1) gene transcription, with the consequent inhibition of c-Jun activation and Activator Protein-1 (AP-1)-dependent transcription." (PMID 23724959, 2013).
colon carcinoma (continued). "In addition, miR-21 regulates colon cancer intravasation and metastasis of colon cancer by targeting PDCD4 for down regulation." (PMID 23272133, 2012). "Recently, PDCD4 has been shown to be regulated by miR-21 in other cancers, such as colon carcinoma." (PMID 20831814, 2010). "Furthermore, PDCD4 down-regulation was shown to enhance invasion of colon cancer cells, by down-regulation, at least in part, of the transcription factor AP-1 components (c-Jun and c-Fos)." (PMID 20831814, 2010). "In colon cancer, PDCD4 levels were continuously lower in the normal-adenoma-carcinoma sequence." (PMID 20831814, 2010). "Programmed cell death 4 (PDCD4) is considered a tumor suppressor gene and is frequently down-regulated in several types of cancers, such as lung cancers, pancreatic cancers, hepatocellular carcinomas, colon cancers, skin carcinomas, invasive ductal breast carcinomas, and gliomas." (PMID 30687637, 2018). "In colon carcinoma, SIN1 translation is controlled by programmed cell death 4 protein (Pdcd4), which inhibits the translation initiation factor 4A (eIF4A)." (PMID 38270460, 2024). "miR‐21 has been shown to drive chemoresistance by targeting PDCD4, PTEN or other genes in several solid tumours, such as renal carcinoma, hepatocellular carcinoma, colon carcinoma and gastric cancer cells." (PMID 33270982, 2021). "Our data suggest that p32 participates in the down-regulation of PDCD4 in colon cancer cells since when p32 expression is blocked in RKO cells, an increase in PDCD4 levels is generated." (PMID 34136383, 2021). "Asiatic acid affects migration, invasion, and apoptosis of colon cancer SW480 and HCT116 cells; it regulates Pdcd4 through the PI3K/Akt/mTOR/p70S6K signaling pathway and inhibits migration and invasion and induces apoptosis of the colon cancer cells." (PMID 32104680, 2020). "The expression of programmed cell death 4 (PDCD4), a tumor suppressor protein that inhibits tumor development in many cancer types, is decreased in CRC and this downregulation in colon tumors has been related to worse prognosis." (PMID 32410997, 2020). "In fact, successive research work on these target molecules including PDCD4, was also important for the elucidation of effect of miR-21 ASO on colon carcinoma cells." (PMID 26236156, 2015). "On the other hand, PDCD4 is an important tumor suppressor gene, which is found in low levels or absent in colon cancer cells." (PMID 34136383, 2021). "Moreover, a COX-2 inhibitor, NS-398, increases PDCD4 in HCA-7 cells, a colon cancer cell line, in agreement with our observation that is consistently downregulated by COX-2 overexpression in carcinoma cell lines." (PMID 32410997, 2020). "In addition to PDCD4, AR inhibition also upregulated phosphatase and tensin homolog (PTEN), another miR-21 target, as well as forkhead box O3A (FOXO3a) in HT29, SW480, and Caco-2 colon cancer cells." (PMID 39055885, 2024). "In the development of colon cancer, tumor-derived exosomes can mediate this process through a variety of ways, such as targeting thioesterase superfamily member 4- (THEM4-) mediated PI3K/AKT and NF-κB pathways, targeting programmed cell death protein 4 (PDCD4)." (PMID 35845138, 2022). "Investigations haverevealed that PDCD4 could inhibit c-Jun activation, as well as activating transcriptionfactor-1 (AP-1)-dependent transcription through the downstream MAP4K1/JNK/AP-1 signalingpathway, in colon carcinoma cells." (PMID 27240294, 2016). "However, in colon cancer cells, PDCD4 did not alter cell cycle progression or induce apoptosis." (PMID 22272332, 2012).
glioblastoma (49 papers, 2012 to 2026). The most malignant astrocytic tumor (WHO grade IV). "Enhancement of miR-21 expression is associated with increased cell proliferation, PDCD4 and Sprouty repression, and chemotherapy resistance in models of cardiac hypoxia preconditioning, pulmonary artery smooth muscle cells, glioblastoma and ovarian tumors." (PMID 23272113, 2012). "Programmed cell death 4 (PDCD4) is a newly identified tumour suppressor and has been demonstrated to inhibit neoplastic transformation and its loss of expression is associated with glioblastoma." (PMID 25991676, 2016). "Depletion of PDCD4 in glioblastoma (GBM) cells resulted in decreased levels of certain eIF3 subunits, including eIF3F." (PMID 42123540, 2026). "In glioblastoma-derived cell lines, the suppression of miR-21 restored the PDCD4 expression and promoted apoptosis." (PMID 40461641, 2025). "Reduction of STAT1 in glioblastoma cell lines by knock down experiment significantly increased PDCD4 expression and decreased PDCD4 targets in Glioblastoma cell lines." (PMID 37476290, 2023). "Downregulation of hnRNPC in glioblastoma inhibited its binding to miRNA-21, which suppressed the Akt pathway via upregulation the expression of programmed cell death 4 (PDCD4)." (PMID 35355828, 2022). "miR-21 has been shown to affect the carcinogenesis of malignant peripheral nerve sheath tumors, glioblastoma and neuroblastoma through modulation of PDCD4." (PMID 35402235, 2022). "The role of PDCD4 during apoptosis is further exemplified in glioblastoma cells that overexpress miRNA-21, a microRNA which inhibits PDCD4 translation and also impedes PDCD4- dependent apoptosis." (PMID 35847932, 2022). "This resulted in an increase in PDCD4 expression within the glioblastoma cells and subsequent increased sensitivity to Temozolomide." (PMID 34069860, 2021). "The E3 ubiquitin ligases β-transducin repeat-containing protein 1/2 (βTRCP1/2) have been shown to be required for the proteasome-mediated degradation of PDCD4 in the T98G glioblastoma cell line." (PMID 34617965, 2021). "Previous work in T98G glioblastoma cells has shown that phosphorylation of Ser67, Ser71, and/or Ser76 in the βTRCP-binding region of PDCD4 is necessary for βTRCP binding and subsequent proteasome-mediated degradation of PDCD4." (PMID 34617965, 2021). "PDCD4 is also considered a transcription inhibitor due to its ability to bind the p65 subunit of nuclear factor-kappa B (NF-κB) in human glioblastoma cells, Twist1, and specific protein (Sp) family transcription factors." (PMID 31952347, 2020). "The downregulation of PDCD4 is observed in different types of cancer, such as colorectal carcinoma, prostate cancer, glioblastoma, lung cancer, and hepatocellular carcinoma." (PMID 31952347, 2020). "PDCD4 was reported to directly bind with NFκB/p65 and suppressed NFκB-dependent transcription in human glioblastoma." (PMID 32416730, 2020). "HNRNPC, whose specific siRNA was reported to inactivate Akt pathway was also identified to control the metastatic potential of glioblastoma by regulating PDCD4." (PMID 31019526, 2019). "We found that microRNA-503 increases proliferation of glioblastoma cells and inhibits apoptosis by directly targeting PDCD4." (PMID 28912531, 2017). "On the other hand, over-expression of PDCD4 leads to decreased proliferation and increased apoptosis in glioblastoma-derived cell lines, while its down-regulation by miR-21 facilitates glioblastoma proliferation in vivo." (PMID 29091952, 2017). "We recently demonstrated that the loss of PDCD4 in Glioblastoma multiforme (GBM) tumours correlates with an increase in Bcl-xL expression, and that re-expression of PDCD4 results in down-regulated Bcl-xL expression and increased sensitivity to chemotherapeutics." (PMID 26595526, 2016).
glioblastoma (continued). "Here, we demonstrate that ADAR2 strongly down-modulates miR-21 and up-regulates PDCD4 protein (PDCD4 is a validated miR-21 target gene) and that this has important consequences in inhibiting glioblastoma cell migration." (PMID 25582055, 2015). "Here, we demonstrate that the expression of ADAR2 in glioblastoma cells can significantly down-modulate miR-21 and up-regulate PDCD4 protein levels in the U118 and A172 cell lines." (PMID 25582055, 2015). "Based on the prediction of computer-aided algorithms, the tumor suppressor gene, Pdcd4, has been validated as a miR-21 target in human urothelial carcinoma and glioblastoma cells." (PMID 23469214, 2013). "Furthermore, HNRNPC regulates microRNA-21 (miR-21) expression, thereby affecting glioblastoma progression via Programmed Cell Death 4 (PDCD4)." (PMID 38474421, 2024). "Additionally, the deletion of PDCD4 contributed to the development of chemoresistance in models of glioblastoma multiforme." (PMID 36552834, 2022). "Moreover, over-expression the PDCD4-targeting miR-96 has been shown to promote resistance of glioblastoma cells to radiotherapy." (PMID 35402235, 2022). "Moreover, we analyzed the level of PDCD4 mRNA using qRT-PCR in glioblastoma cells transfected with miR-503 inhibitor or mimics." (PMID 28912531, 2017). "Additionally, miR-21 was shown to down-regulate the expression of the tumor suppressor PDCD4 in the human glioblastoma cell line T98G." (PMID 28060761, 2017). "Controls aggressiveness of glioblastoma cells through the regulation of PDCD4." (PMID 27259278, 2016). "Interestingly, although there is increased expression of both cytoplasmic HuR and miR-21 in primary Glioblastoma cells, the expression of PDCD4 in these cells is reduced." (PMID 26595526, 2016). "Studies have demonstrated that exosomes from macrophages in glioblastoma multiforme (GBM) patients contain miRNA-21, which inhibits the expression of the tumor suppressor gene PDCD4 in recipient GBM cells." (PMID 40141358, 2025). "And they showed that overexpression of miR-503 in glioblastoma cells increased cell proliferation, and reduced cell apoptosis by targeting PDCD4 (programmed cell death 4)." (PMID 33762949, 2021). "Prominent oncomiR miR-21, for instance, is overexpressed in glioblastoma multiforme (GBM) and colorectal cancer (CRC), where it suppresses the expression of tumor suppressors like PTEN and PDCD4, therefore promoting greater proliferation, invasion, and chemoresistance." (PMID 40581650, 2025). "In addition, previous studies had reported that miR-93-5p or PDCD4 regulated PI3K/Akt pathway in lung cancer, glioblastoma, brain stroke, and other diseases." (PMID 37308277, 2023). "For example, miR-21 is often upregulated in glioblastoma multiforme (GBM), where it targets PTEN and PDCD4, driving proliferation and tumor progression." (PMID 40943278, 2025). "Strikingly, silencing of HNRNPC lowered mi-R-21 levels in turn increased the expression of programmed cell death 4 (PDCD4), suppressing AKT serine/threonine kinase (Akt) and Ribosomal protein S6 kinase beta-1 (p70S6K) activation and inhibiting migration and invasion in glioblastoma." (PMID 35625706, 2022).
lung carcinoma (47 papers, 2004 to 2026). "Berberine, another plant-derived compound, reduces the viability of colon and lung cancer cells by inducing apoptosis and activating caspase-3 and the miR-21/programmed cell death protein 4 (PDCD4) axis associated with tumor progression." (PMID 41050082, 2025). "Our results were consistent with the findings in human hepatocellular carcinoma and lung cancer where loss of Pdcd4 expression was found in cancer compared with normal tissues." (PMID 19728867, 2009). "Similarly, a reduction in the levels of nuclear PDCD4 in lung carcinoma cells was linked to tumor progression, which was consistent with our findings." (PMID 36552834, 2022). "PDCD4 was also shown to be an independent risk factor in colon and lung cancer." (PMID 20831814, 2010). "In addition, loss of PDCD4 expression in human lung cancer cells has been shown to correlate with tumor progression and poor prognosis." (PMID 19602286, 2009). "Additionally, the expression of PDCD4 (a tumor suppressor highly associated with lung cancer) in NSCLC cells with low endogenous levels was attenuated by SND1 silencing, implying that SND1 might function as a molecular regulator upstream of PDCD4." (PMID 39885142, 2025). "After the expression of PDCD4 is suppressed, PDCD4 cannot effectively inhibit the activity of the protein translation initiation factor eIF4A, which promotes the proliferation and invasion of lung cancer cells." (PMID 41394878, 2025). "As a tumor suppressor, PDCD4 is frequently expressed at low levels in various tumor types including lung cancer." (PMID 39885142, 2025). "Understanding the PDCD4–p62 axis offers promising insights for developing novel strategies to improve treatment outcomes in lung cancer." (PMID 38891090, 2024). "Programmed cell death 4 (PDCD4) acts as a tumor suppressor in lung cancer by reducing the expression of p62, a protein involved in autophagy, thereby inhibiting cell proliferation and tumorigenesis while promoting apoptosis." (PMID 38891090, 2024). "Exosomal miR-21 derived from lung cancer cells targets PDCD4 to promote osteoclastogenesis and the bone metastasis of lung cancer." (PMID 36428785, 2022). "The inhibitory role of miR-182 on PDCD4 is involved in the modulation of sensitivity of lung cancer cells to cisplatin." (PMID 35402235, 2022). "miR-182 silencing has inhibited growth and invasive properties of lung cancer cells through modulation of PDCD4 levels." (PMID 35402235, 2022). "The expression of p62 decreases by programmed cell death 4 (PDCD4), and suppresses the cell proliferation and tumorigenesis and induces the apoptosis in lung cancer cells." (PMID 33375363, 2020). "Diminished PDCD4 expression was previously reported in head and neck squamous cell carcinoma, lung cancer, bladder cancer, and colon adenocarcinoma compared to normal tissues." (PMID 29091952, 2017). "PDCD4 phosphorylation by S6K2 causes its degradation and leads to survival and chemoresistance in lung cancer cells." (PMID 27491285, 2016). "In our preliminary analysis, we found increased miR-21 levels and decreased PDCD4 expressions in lung cancer cell lines (H2030, H460, H23, and A549) compared to those found in normal lung epithelial cells (BEAS-2B and NL-20)." (PMID 27323401, 2016). "To confirm these results, we examined the basal levels of miR-21 and PDCD4 in a variety of lung cancer cell lines." (PMID 27323401, 2016). "Of important, overexpression of PTEN and PDCD4 blocked the pro-cancer activity of miR-21 in lung cancer outgrowth." (PMID 27286259, 2016). "Our results showed increased miR-21 levels and decreased PDCD4 expression in the lung cancer cells (H2030, H460, H23, and A549) compared to normal lung epithelial cells (BEAS-2B and NL-20)." (PMID 27323401, 2016).